MIR611 (microRNA 611)
Synonyms: hsa-mir-611; MIRN611
Gene: MicroRNA gene on chromosome 11 (61,792,495 to 61,792,561, reverse strand). Ensembl gene ENSG00000284108.
Gene Ontology:
Biological process: miRNA-mediated post-transcriptional gene silencing
Cellular component: RISC complex